FOXO1 (forkhead box O1)
Diseases named in the same sentence as FOXO1 in open-access papers (continued):
Sharing a sentence is not in itself a finding about the gene and the disease.
bladder cancer (continued). "The negative regulation of PHLPP2 and FOXO1 by miR-135a leads to dysregulation of phosphorylated Akt, p21, p27, CyclinD1 and Ki67, indicating that miR-135a plays an essential role in bladder cancer progression through Akt-mediated signaling." (PMID 25888950, 2015). "Our study reveals for the first time that miR-135a acts as an onco-miR and promotes cell proliferation by reducing FOXO1 expression in bladder cancer." (PMID 25888950, 2015). "Currently, we demonstrate that PHLPP2 and FOXO1 are the direct targets of miR-135a and that silencing PHLPP2 or FOXO1 plays a crucial role in miR-135a-induced proliferation of bladder cancer cells." (PMID 25888950, 2015). "Since both PHLPP2 and FOXO1 are the negative regulators of Akt signaling pathway, the regulatory mechanism of these two regulators during bladder cancer progression arouses attention." (PMID 25888950, 2015). "Consist with previous studies, our results suggested that PHLPP2 and FOXO1 are both downregulated by miR-135a in bladder cancer cells, and mediated miR-135a-induced cell proliferation." (PMID 25888950, 2015). "To explore the mechanism of miR-135a-induced cell proliferation, we investigated potential targets of miR-135a and found that PHLPP2 and FOXO1 are directly targeted by miR-135a and are essential for the bio-function of miR-135a in bladder cancer." (PMID 25888950, 2015). "Suppression of PHLPP2 or FOXO1 by miR-135a, consisted with dysregulation of p21, p27, Cyclin D1 and Ki67, play important roles in bladder cancer progression." (PMID 25888950, 2015). "Suppression of PHLPP2 or FOXO1, followed with dysregulation of p21, p27, CyclinD1 and Ki67, play critical roles during miR-135a-mediated bladder cancer cells proliferation." (PMID 25888950, 2015). "The results of cell viability MTT and the colony formation assay both indicated that suppression of PHLPP2 or FOXO1 in cells transfected with miR-135a inhibitor dramatically increased the proliferation of bladder cancer cells." (PMID 25888950, 2015). "Moreover, ChIP assay in bladder cancer cells revealed the binding of ERβ to the promoter region of FOXO1." (PMID 40486871, 2025). "As common changes in gene expression upon treatment with entinostat and JQ1 in the four investigated bladder cancer cell lines, we have discovered an upregulation of p21, FOXO1, and Bim, all of which will at least in part contribute to the observed synergistic effect with cisplatin." (PMID 39409994, 2024). "Moreover, there were pieces of evidence indicating that CDC20 accounted for the promotion of radio-resistance of bladder cancer by inducing the degradation of FoxO1." (PMID 35622386, 2022). "When the mRNA expressions of FOXO1/3/4 were less than 1.475, 1.305 and 1.295, respectively, we could primarily diagnose the patient with bladder cancer." (PMID 29221208, 2017). "Collectively, these results suggested that miR-135a directly targets FOXO1 in bladder cancer cells." (PMID 25888950, 2015). "Thus, miR-135a plays essential role during the regulation of PHLPP2 and FOXO1, followed with activation of Akt related pathway in bladder cancer cells." (PMID 25888950, 2015). "We additionally showed that FOXO1, which could be inactivated via the ERβ pathway was also inactivated in cisplatin-resistant bladder cancer cells and that FOXO1 knockdown or inhibitor treatment significantly induced resistance to cisplatin in bladder cancer cells." (PMID 33796076, 2021). "Indeed, the increase of miR-145 decreases FoxO1 expression in metastatic T24T bladder cancer cells." (PMID 31013615, 2019). "ERβ was found to inactivate FOXO1 and reduce the expression of GULP1 via binding to their promoters in bladder cancer cells and thereby induce sensitivity to cisplatin." (PMID 40486871, 2025). "In bladder cancer cells, miR-145 expression inhibited STAT3 activation, stimulated FOXO1 expression, and suppressed cell growth." (PMID 37834058, 2023).
bladder cancer (continued). "Our previous studies have shown that FOXO1 and MMP2 are targeted by the anticancer compound ISO for its suppression of bladder cancer invasion." (PMID 36293387, 2022). "miR-135a acts as an onco-miRNA to promote proliferation of a bladder cancer cell by targeting PHLPP2 and FOXO1." (PMID 32617074, 2020). "(a) Muscleblind‐like 1 antisense RNA 1 (MBNL1‐AS1) suppresses bladder cancer (BC) cell proliferation, (b) MBNL1‐AS1 promotes BC cell apoptosis, and (c) MBNL1‐AS1 regulates BC progression via miR‐135a‐5p/PHLPP2/FOXO1 axis." (PMID 31769229, 2020). "It is confirmed that miR-135a promotes bladder cancer cells proliferation and tumorigenicity by suppressing endogenous PHLPP2 and FOXO1 expression, and that PHLPP2 and FOXO1 suppression are essential for miR-135a-mediated cell proliferation in bladder cancer." (PMID 25888950, 2015). "Our study demonstrates that miR-135a promotes cell proliferation in bladder cancer by targeting PHLPP2 and FOXO1, and is performed as an onco-miR." (PMID 25888950, 2015). "Similarly, in bladder cancer, miR-1 mediates tumor suppression by directly targeting Golgi phosphoprotein 3 (GOLPH3), inhibiting FOXO1 and AKT phosphorylation." (PMID 41373864, 2025).
Sepsis (40 papers, 2011 to 2026). Sepsis is defined as life-threatening organ dysfunction caused by a dysregulated host response to infection. "Since CD8+ T cells mediate pathogen-specific immunity through targeted cytotoxic responses 47, these results suggest that myeloid FoxO1 deficiency promotes Tim4+ macrophage-driven enhancement of CD8+ T cell-mediated responses during sepsis." (PMID 41362741, 2026). "Another study indicated that miR-223 level is negatively associated with lymphocyte apoptosis by targeting FOXO1 during sepsis." (PMID 36119054, 2022). "The rs2721068 and rs17446614 SNPs were shown for the first time to correlate to sepsis, and they were also the first SNPs in the FOXO1 gene to be associated with sepsis." (PMID 31492105, 2019). "Our study demonstrated for the first time that the rs2721068 and rs17446614 FOXO1 SNPs are correlated with the genetic predisposition to sepsis." (PMID 31492105, 2019). "In this study, we found that rs2721068 and rs17446614 in the FOXO1 gene were correlated with the genetic predisposition to sepsis after conducting whole-exome sequencing and validation analyses." (PMID 31492105, 2019). "Another important finding of the present study was that FOXO1 had diagnostic valueamong patients with severe sepsis and septic shock." (PMID 24303815, 2014). "Secondly, FOXO1 can be used as a diagnostic biomarker forpatients with sepsis and can be a predictor of the prognosis of patients with sepsis." (PMID 24303815, 2014). "Several previous reports provided evidence that sepsis is associated with loss of muscle mass and upregulated expression and activity of FOXO1, atrogin-1 and MuRF1." (PMID 23555761, 2013). "Our findings suggest that targeting FoxO1 in macrophages may represent an effective therapeutic strategy for sepsis-associated intestinal injury." (PMID 41362741, 2026). "FOXO1 also plays important roles in sepsis-associated diseases." (PMID 39833662, 2025). "Here, we tested the hypotheses that FOXO1 activation and loss of muscle mass induced by glucocorticoids and sepsis is regulated by PPARβ/δ and that inhibition of PPARβ/δ activity can prevent muscle wasting in these conditions." (PMID 23555761, 2013). "In several murine models of muscle loss FoxO1 mRNA is increased including different sepsis models." (PMID 21483870, 2011). "Our study demonstrated that myeloid-specific FoxO1 knockout alleviates intestinal injury in sepsis and that FoxO1, as a key transcription factor, regulates Tim4+ macrophages during septic intestinal injury." (PMID 41362741, 2026). "Together, these findings suggest that Tim4+ macrophages exert anti-inflammatory effects resembling the M2 phenotype, mediated in part through FoxO1-dependent glycolysis during sepsis." (PMID 41362741, 2026). "In conclusion, our findings demonstrate that UTI alleviates SALI by disrupting an Ang-2-mediated vicious cycle via the PI3K/Akt/FoxO1 pathway, revealing a novel mechanistic insight into its therapeutic action against sepsis-induced vascular leakage." (PMID 42048334, 2026). "In young survivors, cardiac Foxo1 and its downstream effector Trim63 (MuRF1) protected from sepsis-induced cardiac remodelling, multi-organ injury and mortality." (PMID 41535469, 2026). "Reports have suggested that FOXO1 levels are increased in the skeletal muscles of sepsis animal models." (PMID 39833662, 2025). "In addition, FOXO1 is an important factor in proteolysis, and increased FOXO1 expression during sepsis is a key factor that causes SAW.This suggests that copper-induced cell death may be involved in the pathomechanism of SAW through the FOXO-related signaling pathway." (PMID 40182687, 2025). "Overexpression of miR-223-3p has been shown to suppress FOXO1 expression, thereby reducing autophagic activity and preventing immune cell dysfunction in sepsis." (PMID 40135054, 2025).
Sepsis (continued). "We also found that CXCL12 induced FoxM1 expression in lung ECs via p110γ PI3K→ FoxO1 signaling and mediating endothelial regeneration in sepsis-induced inflammatory lung injury." (PMID 33804745, 2021). "Our research first proved the vital role of miR-223 in cell survival and proliferation via regulation of FOXO1 in sepsis, in accordance with the function of FOXO1." (PMID 33077816, 2020). "We conclude that miR-223 can serve as a protective factor in sepsis by reducing apoptosis and enhancing cell proliferation in lymphocytes by interacting with FOXO1." (PMID 33077816, 2020). "For rs17446614, the levels of FOXO1 in sepsis patients with the A/A-A/G and G/G genotypes were significantly lower than in the normal controls (p = 0.014 and p < 0.001, respectively)." (PMID 31492105, 2019). "After validation, SNPs located in the Forkhead box O1 (FOXO1) gene were proven to be related to sepsis, and the serum levels of FOXO1 in individuals with different FOXO1 genotypes were also evaluated." (PMID 31492105, 2019). "For rs2721068, the levels of FOXO1 in sepsis patients with the T/T and T/C-C/C genotypes were significantly lower than in the normal controls (p < 0.001 and p = 0.004, respectively)." (PMID 31492105, 2019). "Lc3b and Sqstm1 increased in the DIA after 24 and 48 h of sepsis while Foxo1 only increased after 24 h." (PMID 31660704, 2019). "As a next step, additional SNPs in FOXO1 will be analyzed, and additional studies are needed to determine the roles of rs2721068 and rs174466614 in the sepsis pathway." (PMID 31492105, 2019). "Lc3b and Bnip3 increased in the TA after 24, 48, and 96 h of sepsis, while Sqstm1 and Foxo1 increased after 24 and 48 h." (PMID 31660704, 2019). "The serum levels of FOXO1 in sepsis patients with the T/C-C/C genotype were significantly higher than in sepsis patients with the T/T genotype (p = 0.002)." (PMID 31492105, 2019). "Sepsis‐induced increases in Lc3b, Sqstm1, Bnip3, and Foxo1 mRNA levels were relatively higher in the TA than in the DIA." (PMID 31660704, 2019). "We reported for the first time that the rs2721068 in dominant model and rs17446614 in recessive model were correlated to sepsis and serum levels of FOXO1 in these genotypes were all significantly higher in normal controls than in sepsis patients." (PMID 31492105, 2019). "The serum levels of FOXO1 in sepsis patients with any genotype were significantly lower than in normal controls." (PMID 31492105, 2019). "This indicates thatthe levels of ACVR2A and FOXO1 were lower in patients with sepsis than in normal controls becausethey are the common target genes of miR-223, miR-15a andmiR-16." (PMID 24303815, 2014). "In this sense, sepsis increases FoxO1 mRNA levels as well as nuclear FoxO1 levels and DNA binding activity in gastrocnemius muscle, but not in the heart." (PMID 25294954, 2014). "Levels of ACVR2A (P<0.01) and FOXO1(P<0.01) were significantly different among normal controls, patients withsepsis, patients with severe sepsis and patients with septic shock." (PMID 24303815, 2014). "Atrogene induction through FoxO1 and FoxO3a activation is a crucial step in the process leading to muscle atrophy during sepsis." (PMID 25294954, 2014). "FOXO1 is involved in glucocorticoid- and sepsis-induced muscle wasting, in part reflecting regulation of atrogin-1 and MuRF1." (PMID 23555761, 2013). "The present study provides the first evidence of a PPARβ/δ-FOXO1-atrogin-1/MuRF1 pathway in glucocorticoid- and sepsis-induced muscle wasting." (PMID 23555761, 2013).
Sepsis (continued). "The present results suggest that the transcription factor PPARβ/δ regulates FOXO1 expression in skeletal muscle and plays an important role in glucocorticoid- and sepsis-induced muscle wasting." (PMID 23555761, 2013). "Conversely, in aged hosts, Foxo1 and Trim63 acted as drivers of sepsis pathogenesis and death." (PMID 41535469, 2026). "Therefore, we first performed network pharmacology analysis to evaluate the effect of HSBD on FoxO1 in sepsis." (PMID 41362741, 2026). "This suggests that HSBD may serve as a promising therapeutic strategy targeting FoxO1 in sepsis-related conditions." (PMID 41362741, 2026). "Forkhead Box O1 (FoxO1) is a critical transcription factor involved in regulating inflammatory responses; however, its role in sepsis-induced intestinal injury remains unclear." (PMID 41362741, 2026). "Our previous study has shown that the inhibition of ATP citrate lyase (ACLY)-related gluco-lipogenesis could ameliorate sepsis-induced multiple organ dysfunction via inhibiting FoxO1-MYC-mediated vascular activation." (PMID 40369168, 2025). "Therefore, we demonstrate that miR-223 affects the level of autophagy in CD4+ T lymphocytes via the regulation of FOXO1, thereby affecting the development of sepsis." (PMID 39439897, 2024). "Mechanistically, these phenomena can be attributed to the LXR agonists enhancing SIRT1 signaling, thereby boosting the antioxidant level of FOXO1 and resistance to endoplasmic reticulum stress, as well as deacetylating NF-κB, which in turn mitigates sepsis-induced myocardial injury and dysfunction." (PMID 38690282, 2024). "In a model using cultured muscle cells, one group tested the hypothesis that PPARδ upregulates FOXO1 activity in muscle, thereby upregulating MAFbx and MuRF1 expression during sepsis and glucocorticoid treatment." (PMID 34575939, 2021). "Therefore, we aimed to address the potential role of miR-223 in apoptosis by regulating FOXO1 in sepsis." (PMID 33077816, 2020). "TGF-β secreted by MSCs could skew LPS-stimulated macrophage polarization towards the M2-like phenotype, reduce inflammatory reactions, and improve the phagocytic ability via the Akt/FoxO1 pathway, providing potential therapeutic strategies for sepsis." (PMID 31771622, 2019). "Another study by our group reported that the serum levels of FOXO1 in normal controls were significantly higher than in sepsis patients, and the values of FOXO1 were also significantly different between survivors and non-survivors according to 28-day mortality." (PMID 31492105, 2019). "Finally, our previous study first reported that serum FOXO1 levels were lower in sepsis patients than in normal controls, which is consistent with our present results." (PMID 31492105, 2019). "Next, we evaluated the serum levels of FOXO1 in 30 normal controls and 30 sepsis patients." (PMID 31492105, 2019). "In previous studies, sepsis in rats was associated with increased expression of the GR in skeletal muscle and sepsis-induced muscle wasting as well as expression of atrogin-1, MuRF1, and FOXO1 were prevented by treatment with the glucocorticoid receptor antagonist RU38486." (PMID 23555761, 2013). "The present results suggest that PPARβ/δ regulates FOXO1 activation in glucocorticoid- and sepsis-induced muscle wasting and that treatment with a PPARβ/δ inhibitor may ameliorate loss of muscle mass in these conditions." (PMID 23555761, 2013). "Indeed, transcriptional analyses of the hearts of the polymicrobial sepsis LD50 survivors demonstrated a unique infection-inducible cardiac transcriptome that revealed a FoxO1-dependent disease tolerance mechanism that was necessary to enable mice to survive a polymicrobial systemic challenge." (PMID 40961093, 2025). "Similarly, the increased expression of FoxO1 upon sepsis and its subsequent DNA binding activity was controlled by the GR activity (by contrast with FoxO3a), further suggesting a tight collaboration between these GR and FoxO1." (PMID 32933049, 2020).